SERTAD4 (SERTA domain containing 4)
Synonyms: DJ667H12.2
Tractability: No criterion of Open Targets' tractability assessment is met for any kind of drug.
Gene: Protein-coding gene on chromosome 1 (210,232,596 to 210,246,631, forward strand). Ensembl gene ENSG00000082497.
Subcellular location (Human Protein Atlas): Nucleoplasm
Gene Ontology:
Molecular function: protein binding
Cellular component: nucleoplasm; nucleus
Genetic constraint (gnomAD): Loss-of-function variants: 16 observed, 27.81 expected, observed/expected ratio (o/e) 0.58, 90% interval 0.39 to 0.87. The upper end of that interval is the gene's LOEUF score, 0.87, which puts it in group 3 of 6, group 1 being the genes least tolerant of losing a copy. Missense variants: 351 observed, 399.13 expected, observed/expected ratio (o/e) 0.88, 90% interval 0.81 to 0.96. Synonymous variants: 140 observed, 147.72 expected, observed/expected ratio (o/e) 0.95, 90% interval 0.82 to 1.09.
Homologues: Orthologues: chimpanzee SERTAD4 (99% identical), macaque SERTAD4 (97% identical), pig SERTAD4 (92% identical), dog SERTAD4 (91% identical), mouse Sertad4 (81% identical), rat Sertad4 (79% identical), tropical clawed frog sertad4 (54% identical), zebrafish sertad4 (29% identical), Drosophila melanogaster CG2865 (18% identical).
Diseases named in the same sentence as SERTAD4 in open-access papers:
SERTAD4 is named in the same sentence as 7 diseases in open-access papers, as found by Europe PMC text mining. Sharing a sentence is not in itself a finding about the gene and the disease. The quoted sentences say what the papers report.
COVID-19 (2 papers, 2022 to 2024). A disease caused by infection with severe acute respiratory syndrome coronavirus 2. "This phenomenon reflects the discussions in the Introduction that RIPK3 is related to the natural essence of COVID-19, while ATP6V1B2, IFI27, BTN3A1, SERTAD4, and EPSTI1 contain more information about SARS-CoV-2." (PMID 36298522, 2022).
heart failure (2 papers, 2020 to 2024). Inability of the heart to pump blood at an adequate rate to meet tissue metabolic requirements. "Previous research found that SERTAD4 establishes a dependent signalling pathway in the epigenetic reprogramming of heart failure." (PMID 39462261, 2024).
tumor (4 papers, 2017 to 2025). "SERTAD4 plays a crucial role in regulating these interactions, which significantly impacts tumour progression, tumour immune escape mechanisms and the efficacy of immunotherapy." (PMID 39462261, 2024). "After bioinformatics analysis and tumour patient sample revealed potential protective role of SERTAD4 in CRC." (PMID 39462261, 2024). "Retrieving patient data from TCGA‐GTEx (Normal = 359 vs. Tumour = 383), we found that SERTAD4 can distinguish CRC well (AUC = 0.782)." (PMID 39462261, 2024). "In these conditions, the expression of SERTAD4 may indicate its important role in maintaining normal functions of intestinal epithelial cells, and its reduction could facilitate the growth and survival of tumour cells and carcinogenic bacteria." (PMID 39462261, 2024). "Among genes with significantly increased expression in the CD271high subsets were mediators of tumor cell migration e.g. AXL30 and members of the lysyl-oxidase family LOX26 and LOXL231 as well as the less characterized SERTAD4 (SERTA Domain-Containing Protein 4), (SI)." (PMID 28852061, 2017). "However, SERTAD4 has not been reported in any tumours, indicating that its specific functions and mechanisms in tumours present potential research opportunities." (PMID 39462261, 2024).
cancer (2 papers, 2024 to 2025). A tumor composed of atypical neoplastic, often pleomorphic cells that invade other tissues. "Furthermore, we also examined the association between SERTAD4 expression and the infiltration of immune cells in other cancers." (PMID 39462261, 2024). "Analysis using TCGA data revealed that SERTAD4 expression was upregulated in 12 cancer types and downregulated in 7 cancer types (all p < 0.05)." (PMID 39462261, 2024). "Aside from its expression in CRC, we were intrigued to discover if SERTAD4 exhibited variable expression levels across other cancer types." (PMID 39462261, 2024). "After eliminating non‐cancer death patients, the protective effect of SERTAD4 on CRC was further enhanced (HR = 0.648, p = 0.06)." (PMID 39462261, 2024). "Through The Cancer Genome Atlas, Gene Expression Omnibus, Human Protein Atlas, immunohistochemistry, and co‐culture assays, we further confirmed the differential expression of SERTAD4 in CRC." (PMID 39462261, 2024). "These genes include SERTAD4, IRF6, TRAF3IP3, and UTP25, which are involved in embryo development, cancer, innate immune response, and epigenetic processes." (PMID 40007031, 2025).
infection (1 paper, 2024). The state of being infected such as from the introduction of a foreign agent such as serum, vaccine, antigenic substance or organism. "Moreover, both KRAS mutations and FN infection suppress the expression of SERTAD4." (PMID 39462261, 2024). "Moreover, after 12 h of infection with FN (MOI 1:10) in CRC cell lines, we found that FN could also inhibit the expression of SERTAD4 (p < 0.05)." (PMID 39462261, 2024).
SERTAD4 also shares sentences with these, for which no sentence is quoted: colorectal cancer (1 paper); mandibular deficiency (1).